MGMT (O-6-methylguanine-DNA methyltransferase)
Diseases named in the same sentence as MGMT in open-access papers (continued):
Sharing a sentence is not in itself a finding about the gene and the disease.
tumor (continued). "As shown by the forest plots of univariate analysis, similar to various clinical features including age, tumor grade, IDH mutation status, 1p19q codeletion, and MGMT methylation, the risk score could serve as an independent prognostic factor (p<0.001, HR:2.715, 1.698, 2.132)." (PMID 35719998, 2022). "Therefore, MGMT expressed in tumor cells removes the guanine-alkyl group and attenuates the antitumor effect, while patients with MGMT promoter methylation have a better response to temozolomide and a better prognosis because of the suppression of MGMT in tumor cells." (PMID 35397757, 2022). "Thus, MGMT promoter methylation serves as a predictor of tumor responsiveness to alkylating agents." (PMID 35159278, 2022). "In addition, the prognostic signature was also significantly correlated with clinical traits (sex and MGMT promoter status), tumor immunogenicity (mRNAsi, EREG-mRNAsi and HRD-TAI), and immune infiltration (stemness index, immune cells infiltration, immune score, and gene mutation)." (PMID 36389748, 2022). "The response rate to temozolomide was 38% in the MGMT promoter methylated group versus 7% in the group without MGMT promoter methylation, suggesting that a tumor response due to temozolomide may be associated with the presence of MGMT promoter methylation." (PMID 35677534, 2022). "In addition to age, KPS, postoperative standard chemoradiotherapy, the extent of tumor resection, and the status of MGMT, multivariate analysis indicated that the NLR (p = 0.017), PLR (p < 0.001) and SII (p = 0.007) remained independent of prognostic significance." (PMID 36556130, 2022). "Perfusion-weighted and/or diffusion-weighted MRI features have been used to predict EGFR amplification and MGMT-methylation, whereas MR spectroscopy and amino acid tracer PET imaging (FET–PET) can predict IDH1 mutation status due to its effects on tumor metabolism." (PMID 33578746, 2021). "Recent evidence suggested that tumor vascularity may be a modulating factor in combination with methylation of O6-methylguanine-DNA methyltransferase (MGMT) promotor gene on the effect of temozolomide-based therapies, opening new possibilities for personalized treatments." (PMID 34771583, 2021). "Interestingly, this tumor sample was also classified as MGMT methylated." (PMID 34041479, 2021). "Therefore, elevated levels of MGMT activity, defined as non-methylated MGMT, in tumor tissue are associated with resistance to alkylating agents." (PMID 33661424, 2021). "Hypermethylation of tumor-related genes, such as cyclin-dependent kinase inhibitor 2A (CDKN2A), E-cadherin (CDH1), death-associated protein kinase (DAPK), phosphatase and tensin homolog (PTEN), and O6-methylguanine-DNA methyltransferase (MGMT), have been reported in HNC." (PMID 34206840, 2021). "Additionally, patients in the high-risk group exhibited older age, high tumor grade, isocitrate dehydrogenase wildtype, 1p/19q non-codeletion, O-6-methylguanine-DNA methyltransferase promoter unmethylation and poor prognosis." (PMID 34778248, 2021). "Thus, EPR targeted KS90 could be used to deplete tumor MGMT and selectively sensitize tumor cells to the more cytotoxic O6-(2-chloroethyl)guanine assault, thus resulting in synergistic tumor cell kill." (PMID 33419160, 2021). "Furthermore, individual tumor groups considering genetic and molecular subgroups (e.g., IDH and/or TERT mutation, 1p19q co-deletion, O6-methylguanine-DNA-methyltransferase [MGMT] status) should be investigated separately from each other in order to be able to go into more depth." (PMID 34677383, 2021). "Therefore, targeting the MGMT gene may sensitize tumor cells to TMZ and increase treatment efficiency in TMZ-resistant patients." (PMID 34959480, 2021). "Thus, we demonstrated that MGMT methylation is not restricted to neoplasms or strictly associated to distinct pathogens, as well as oncogenic viruses or bacteria." (PMID 33917711, 2021).
tumor (continued). "Moreover, our results show that tumor vascularity may identify a subgroup of patients that exhibit a greater benefit from MGMT methylation." (PMID 33001310, 2021). "Within ARETHUSA, MMR-proficient CRC patient tumors are tested for MGMT expression by immunohistochemistry, and those that are negative (e.g., for MGMT promoter methylation) are treated with temozolomide and then tested for tumor mutational burden in post-temozolomide tumor biopsies." (PMID 34072037, 2021). "Hence, we show for the first time that MGMT hypermethylation occurs in chronic diseases that are not strictly associated to distinct pathogens, oncogenic viruses or neoplasms but that lead to damage of the myelin sheath in various ways." (PMID 33917711, 2021). "While certain patient factors such as tumor molecular signatures and MGMT methylation may portend prolonged survival, as prior studies have shown, extent of resection does matter, with differences in time to tumor progression and overall survival seen between gross and near-total resection." (PMID 33440712, 2021). "Finally, the MGMT level was quantified as a parameter of DNA repair in tumor cells." (PMID 33123485, 2020). "Moreover, ALDH1A3 expression was positively associated with the tumor edema grade and inversely with overall survival (OS) (median OS: 16 months vs 10 months), but with neither MGMT promoter methylation status nor Ki67 index in GBM." (PMID 32680476, 2020). "Thus, the status of MGMT expression may be related to tumor chemosensitivity; however, the relationship between the sensitivity of NENs to alkylating agents and MGMT status is controversial." (PMID 32141507, 2020). "Additionally, half of tumours (5/10) have positive MGMT methylation status." (PMID 33177572, 2020). "There are many potential explanations for this difference, including differences in tumor segmentation and radiomics feature extraction methods, the inclusion of lower grade tumors in other study cohorts, and different testing methods for laboratory determination of MGMT methylation status." (PMID 32678261, 2020). "In addition, MGMT status of tumor cells could also serve as a prognostic indicator of GI-NET G1, independent of the Ki-67 LI." (PMID 33287738, 2020). "Hence, MGMT is considered a promising target for tumor treatment." (PMID 32010632, 2019). "Therefore, MGMT promoter methylation status can be used as a marker for resistance to treatment with alkylating agents, especially in elderly patients, where chemotherapy in un-methylated tumours evidenced minimal benefit." (PMID 31690341, 2019). "Among 5 seropositive patients, the anti‐MGMT‐02 autoantibody peptide level decreased 30 days after surgery; 4 out of the 5 seropositive patients became seronegative, 5 patients with anti‐MGMT‐02 peptide autoantibodies reached preoperative levels again when tumor recurrence developed." (PMID 31210005, 2019). "Therefore, MGMT promoter methylation might not only be predictive for the outcome after primary surgery, but also in tumor recurrence." (PMID 31766430, 2019). "In addition, p16 (MTS, multiple tumor suppressor 1), DAPK (death-associated protein kinase), MGMT (O6-methylguanine-DNA methyltransferase), PI3K (the phosphatidylinositol 3-kinase), c-myc and other genes were investigated in oral tobacco-related tumor tissues and cancer associated adjacent tissues." (PMID 31582940, 2019). "Therefore, intra-tumoral heterogeneity as a partial reason for MGMT promoter methylation changes cannot be excluded and therapy-induced eradication of sensitive tumor clones and clonal expansion of resistant ones may be involved in this phenomenon." (PMID 31766430, 2019).
tumor (continued). "We therefore tested our hypothesis that textural intra-tumor heterogeneity, tumor shape and intensity histogram features computed from radiomics analysis could be used to augment efficacy of predictive biomarkers such as MGMT status." (PMID 30774763, 2019). "Thus, MR30 is a multifaceted molecule, which can be used under multiple contexts: (a) to exert selectivity for the HER family of oncogenes, (b) to induce potent growth inhibition in tumour cells with PTEN, K-RAS, B-RAF mutations and (c) to sensitize tumours that co-express EGFR and MGMT to TMZ." (PMID 30416678, 2018). "Therefore, differential MGMT gene methylation, which has been described in other tumor types, is unlikely to be the dominant mechanism causing lower MGMT RNA expression in this group of pNETs." (PMID 30062048, 2018). "Furthermore, pyrosequencing of promoter methylation in tumor samples can be contaminated with MGMT positive normal cells like leukocytes and endothelial cells and therefore maybe show false positive results." (PMID 29344904, 2018). "Similarly patients with relatively sensitive tumours such as those with MGMT methylation, may have a proportionally greater rate of isolated tract associated regional or distant failure." (PMID 30029668, 2018). "Therefore, the depletion of MGMT is important for increasing tumor sensitivity to temozolomide." (PMID 30583528, 2018). "Inactivation of gene of MGMT could contribute tumor progression." (PMID 29362385, 2018). "High levels of MGMT in tumor tissue may be depleted with pseudo-substrates that resemble 06-MeG." (PMID 29963012, 2018). "Beyond mediating MGMT expression and TMZ sensitivity, enhancer deletion was associated with reduced proliferation in five out of six enhancer-deleted clones, suggesting that K-M enhancer inactivation may also reduce tumor growth." (PMID 30054476, 2018). "Also, the strong potency of the approach against MGMT-proficient tumour cells indicates that type I agents like EG22 may be developed as a potential alternative to TMZ in advanced tumours characterized by MGMT expression." (PMID 28800752, 2017). "However, recent results suggest that patients with a O6-methylguanine DNA methyltransferase (MGMT) promoter-methylated recurrent tumor may benefit from a temozolomide rechallenge." (PMID 28730289, 2017). "Further, we analyzed whether the methylation status of P16, RASSF1A, APC, RARβ, DAPK, CDH13, and MGMT there were differences in the characteristics of gene methylation in different tumor stages (early stage vs. advanced stage) and tumor histotypes (SCC vs. AC)." (PMID 28404957, 2017). "This meta-analysis suggests that MGMT expression may be associated with PA tumor recurrence, but not be related to invasiveness or other clinicopathological indicators." (PMID 28152515, 2017). "The reason why these cases were not responding could be due, among other reasons, to individual tumor resistance to alkylating agents, which is mainly due to overexpression of the MGMT protein, and it is a major and currently unresolved problem with TMZ therapy." (PMID 28524099, 2017). "Furthermore, we investigated the expression of the DNA repair enzyme O6-methylguanine-DNA methyltransferase (MGMT) in the core of the tumor and compared it to the periphery, since MGMT is a strong prognostic and predictive marker for the effect of temozolomide in the upfront GBM treatment." (PMID 27171431, 2016). "However, patients with unmethylated MGMT promoter in the tumor showed only a marginal benefit from addition of temozolomide, with a median survival of 12.7 months (95% CI 11.6–14.4) compared with 11.8 months (9.7–14.1) for patients treated with radiotherapy alone (HR 0.69, 95% CI 0.47–1.02)." (PMID 27643594, 2016). "This variable could lead to an underestimation of the level of MGMT methylation of the tumor cells." (PMID 27542245, 2016).
tumor (continued). "Therefore in the present series of 141 LGG, the molecular characterization (namely IDH status, 1p/19q co-deletion and MGMT promoter methylation) was integrated with the tumor “proliferative trait” (conventional H&E or PHH3-guided mitotic count and Ki-67 index) in term of prognosis definition." (PMID 27049832, 2016). "This could be explained by the heterogeneity of the tumor cell lines which means different cell populations may have different methylation patterns and therefore different MGMT expression levels (including a very low MGMT amount)." (PMID 26447477, 2015). "Since MGMT is a suicide protein that is degraded upon binding to and repairing TMZ-induced O6-methylguanine adducts, it has been hypothesized that inhibition of translation via the mTOR signalling pathway could generate a tumour-specific reduction in MGMT protein and increase TMZ sensitivity." (PMID 24909675, 2014). "Thus, we hypothesized that mitigation of the transcriptional overexpression of MGMT that spares its basal transcription, might sensitize tumor cells to alkylating agents with limited affliction of the hematopoietic system." (PMID 25460932, 2014). "Hence the level of MGMT activity correlates with resistance of tumour cells to TMZ." (PMID 24909675, 2014). "Overcoming MGMT resistance in MB may be reliant on MB tumours being proficient in mismatch repair." (PMID 24887326, 2014). "Thus, tumor sensitivity to TMZ requires both low MGMT levels and a functional MMR." (PMID 24593254, 2014). "Reports on transcriptional silencing of MGMT gene in OSCC have shown that frequency of MGMT promoter methylation ranges from 23 to 56% in tumor tissue as compared to 9% in healthy oral mucosa suggesting that inactivation of this DNA repair mechanism may be a significant event in oral carcinogenesis." (PMID 24991542, 2014). "However, downregulation of MGMT remains an attractive therapeutic strategy for patients with tumours exhibiting unmethylated MGMT promoters if it could be achieved in a tumour specific manner." (PMID 24909675, 2014). "In addition, we have analyzed the methylation status of MGMT promoter in tumor tissue." (PMID 23922679, 2013). "Interestingly, our results suggest that the use of PARP inhibitors might be clinically significant in those patients whose tumour is MGMT-unmethylated and currently derive less benefit from TMZ." (PMID 23510353, 2013). "Therefore, it may be that TMZ treatment eventually depletes MGMT in tumor cells if the MGMT expression is low, or MGMT inactivation may be faster than MGMT synthesis." (PMID 23091742, 2012). "Formaldehyde-responsive miRNAs predicted to modulate MAM-associated genes in mouse brains lacking MGMT include miR-17-5p and miR-18d, which regulate genes involved in tumor suppression, DNA repair, amyloid deposition, and glutamatergic and dopaminergic neurotransmission." (PMID 23060898, 2012). "In this context, it was interesting to observe that tumors with a high rate of MGMT protein positive tumor cells were significantly less necrotic, a finding that may be related to the recently shown decreased tumorigenicity of MGMT expressing cells in preclinical models." (PMID 22214427, 2012). "In addition, MGMT (O6-methylguanine methyltransferase) related parameters were compared with those of volumetry in order to observe possible relevance of this molecule in tumor development." (PMID 22214427, 2012). "However, although cancer cell lines are useful models for the in vivo situation, findings should be validated in patient sample series, and so far immunohistochemical analyses of the MGMT protein level in human tumor samples have been inconclusive when correlated with patient outcome." (PMID 22390413, 2012).
tumor (continued). "In conclusion, this study has provided epigenetic evidence that promoter hypermethylation of all three important GL-associated genes, DNMT1, MGMT and EGFR may play a role in GL progression and the inactivation of these genes is stable even as concerns tumour recurrence." (PMID 22264301, 2012). "To best identify the specific MGMT promoter region most predictive of gene silencing and response to therapy, we determined the methylation status of all 97 CpG sites in the MGMT promoter in tumor samples from 70 GBM patients using quantitative bisulfite sequencing." (PMID 21249131, 2011). "Thus, the relationship between MGMT methylation and metastasis or tumor prognosis might be tissue specific, or possibly coincidental." (PMID 22132162, 2011). "Thus, a further question to be addressed is whether tumour recurrences exhibit the MGMT status as the pre-treatment tumour or a different one." (PMID 21269507, 2011). "O6-methylguanine-DNA-methyltransferase methylation status as a host-specific rather than tumour-specific condition explains why MGMT promoter methylation of the tumour was highly associated with TMZ tolerance in patients requiring more dose reductions or discontinuations." (PMID 20736948, 2010). "This indicates that MGMT may serve as a tumor suppressor in many types of cancer." (PMID 21108794, 2010). "However, MSP-PCR is not quantitative and therefore it was of interest to determine whether variable amounts of MGMT promoter methylation could be detected in these tumors as a function of biological characteristics of the tumor." (PMID 19807915, 2009). "Some evidence also suggests IFNs may downregulate MGMT, increasing tumour cell sensitivity to TMZ." (PMID 19672263, 2009). "However, in our study MGMT promoter methylation status was assessed only on tumour samples, and MGMT promoter methylation may vary among different tissues." (PMID 17024124, 2006). "However, among the six CRs to single-agent DTIC therapy three patients had tumours with high MGMT protein levels (⩾50%), indicating that other factors than MGMT may influence clinical response." (PMID 14562026, 2003). "Reported biomarkers exhibiting comparable dysregulation in both tumor and peritumor tissues include MDM2, E2F2, CDKN2A/p16, ETS-1, MGMT, and multiple microRNAs (e.g., miR-21, miR-96-5p, miR-145-5p)." (PMID 41683639, 2026). "Tumor growth, immune checkpoint expressions (IDO, PD-L1), and key biomarkers (MGMT, Ki67) were analyzed to evaluate tumor dynamics and immune modulation." (PMID 41596406, 2026). "In our study, we compared the TMZR-RGPI score among patients stratified by various clinical characteristics, including age, sex, tumour grade, survival status, IDH status, MGMT promoter methylation status, and chemotherapy status." (PMID 39903772, 2025). "In Case 1, the detection of MGMT promoter methylation in an IDH-wildtype, high-grade tumor prompted treatment with the Stupp protocol, a regimen typically used for GBM." (PMID 40575153, 2025). "Advanced MRI techniques, such as SWI/ADC, detect cellularity differences related to MGMT status, while ASL assesses tumor perfusion differences." (PMID 41584616, 2025). "In the FHSXMU/SPPH cohort, significant differences in pathological grade, MGMT promoter status, IDH genotype, survival status, tumor volume, and survival outcome (HR: 2.553, 95%CI: [1.226–5.315]) between the two subtypes (P < 0.05)." (PMID 41188782, 2025). "Established biomarkers, including IDH1, MGMT, and EGFR, provide crucial insights into the tumor's biology and are essential for guiding therapy decisions." (PMID 40223032, 2025). "Resistance to Tmz in GBM is caused by the DNA direct repair enzyme O6‐methylguanine DNA methyltransferase (MGMT), which is expressed in ~50 % of GBM tumours." (PMID 39969500, 2025). "A heatmap was generated to depict the expression profiles of ATRX, OLIG2, MGMT, and IDH2 in normal and tumor tissues, using Log2(TPM+1) for scaling." (PMID 40282990, 2025).